VCL (vinculin)
Diseases named in the same sentence as VCL in open-access papers (continued):
Sharing a sentence is not in itself a finding about the gene and the disease.
cancer (continued). "Vinculin, however, is paradoxically described as a prognostic marker favoring the migration of cancer cells or as a tumor suppressor stimulating cell anchorage." (PMID 38834194, 2024). "Many TME-related genes (such as VEGFA, MMP14, CCND1, MAP2K1, SLC2A1) and actin cytoskeleton-associated genes (such as ITGB4, ITGA6, ACTG1, VCL) were downregulated, suggesting a less favorable TME and an altered cytoskeleton network in ISO-treated cancer cells." (PMID 38339062, 2024). "Here, we investigated the effect of this amino acid substitution and that of a phosphodeficient Y822F vinculin in cancer cells." (PMID 37248996, 2023). "Other authors have established a relation between cortactin and vinculin overexpression and cancer aggression and resistance, and have also proposed them as promising prognostic and predictive biomarkers." (PMID 37686651, 2023). "Here, we sought to determine, in a cancer model, the consequences of perturbing the mechanosensitive protein vinculin at Y822, an amino acid residue phosphorylated in response to force." (PMID 37248996, 2023). "CCAT1::CASC8 was only recently reported in the fusion catalog generated by DEEPEST fusion, and VCL::ADK was only previously reported in a study of cancer cell lines." (PMID 37323575, 2023). "Previous studies have shown that D. magna exposed to cyclophosphamide, one of the most widely used drugs in cancer chemotherapy, showed upregulation of vinculin, a cytoskeletal protein involved in the regulation of focal adhesions and embryonic development." (PMID 37784038, 2023). "In summary, this work demonstrates that Y822 vinculin modulates ligand binding, focal adhesion morphology, proliferation and migration in cancer cells." (PMID 37248996, 2023). "In this way, Y822C vinculin-expressing cancer cells have increased migratory and proliferative capacities – two attributes essential for tumors to grow and metastasize to distant sites." (PMID 37248996, 2023). "Recent studies in different cancer cells have shown that simulated μG is able to alter the balance of forces at FA sites, where vinculin is enriched, inducing reduced proliferation ability and metastasis activity." (PMID 35662260, 2022). "As such, YAP-1 and Vinculin represent a molecular entry point to better understand the high sensitivity of cancer cells to the changes in mechanical properties of the external environment, including mechanical unloaded condition." (PMID 35662260, 2022). "In particular, S-Benp disturbed lamellipodia formation and the colocalization of vinculin and F-actin in cancer cells." (PMID 36558913, 2022). "The increased expression of vinculin is closely related to the aggressiveness and distant metastasis of cancer, which affects the survival prognosis of the patient." (PMID 33535187, 2021). "It was reported that the expression of VCL was reduced in a variety of cancers and was involved in the invasion, metastasis and apoptosis of tumor cells." (PMID 34923985, 2021). "This heterotypic cancer cell-CAF interaction triggers β-catenin recruitment, α-catenin/vinculin interaction, and actin remodeling, allowing CAFs to exert an intercellular physical force on cancer cells and promote cooperative tumor invasion." (PMID 32546182, 2020). "Cancer cells that lose expression of vinculin show enhanced metastasis as well as resistance to apoptosis." (PMID 32231055, 2020). "With respect to the mechanisms by which ERα inhibits cancer matastasis, we focused on the regulation of ERα to vinculin expression based on transcriptome sequence analysis." (PMID 28266545, 2017). "Collectively, these results demonstrate that NME2-mediated regulation of vinculin favors a signaling pathway that contributes to invasiveness and metastasis of cancer cells." (PMID 25249619, 2014). "Previous studies reported that vinculin-mediated focal adhesion is a calcium dependent process that is involved in cancer cell migration." (PMID 23736792, 2013).
cancer (continued). "In high-grade dysplastic cervical cells filamin, vimentin and vinculin were upregulated in contrast to the findings in cancer cells in our study." (PMID 19367286, 2009). "Vinculin can regulate the ability of cancer cells to move away from tumors and spread cancer to other parts of the body." (PMID 18847500, 2008). "Additionally, vinculin, zinc finger protein 521, and neural cell adhesion molecule L1 are known to play roles in cancer development, proliferation, and metastasis, and underscored significant elevation in expression levels as well." (PMID 39801758, 2025). "Previous studies have shown that vinculin is abnormally expressed in highly invasive and metastatic tumor cells and participates in other signaling pathways that affect the occurrence and development of malignant tumors." (PMID 41354982, 2025). "Additionally, cancer disease pathways showed 37 proteins at high levels, including integrin beta-3, integrin alpha-IIb, vinculin, actin, cytoplasmic 1, Ras-related protein Rap-1b, and talin-1." (PMID 40564899, 2025). "Notably, in conjunction with vinculin, it exhibited localization to the ringed structure of invadopodia, consequently fostering cancer progression." (PMID 37737201, 2023). "The decreased protein levels and cell morphologies of the vinculin knockout cell line generated in this study are in good agreement with the phenotypes previously reported when vinculin is deleted, thereby suggesting that our vinculin knockout system in cancer cells is behaving appropriately." (PMID 37248996, 2023). "However, in vivo studies must elucidate and decipher the focal adhesion distribution and localization regarding post-treatment with anti-tumor agents in cancer cells to establish the correlation between knockout of vinculin and restricted cell motility." (PMID 36052248, 2022). "Among all miRNAs that may be associated with VCL, we found that miR-663b was upregulated in various cancers and had a 7 bp binding site with the VCL mRNA 3′-UTR." (PMID 34923985, 2021). "The gene expression of VCL was reduced in the MCS of cancer cells compared with 1g samples." (PMID 34445479, 2021). "Indeed, vinculin preferentially localizes inside the cytosol, thus losing contact with actin filament and impairing the migrating and invasive capabilities of cancer cells, as previously reported." (PMID 31052313, 2019). "The Kaplan plots suggest various possibilities with respect to the role that vinculin may play in cancer progression." (PMID 29899821, 2018). "To test this hypothesis, we examined interactions among cell migration, Ca2+ mobilization, and vinculin (focal complexes) in cancer cells." (PMID 23736792, 2013). "VCL might affect cancer development through the focal adhesion pathway." (PMID 34112125, 2021). "Likewise, vinculin is an adhesion related protein whose expression is negatively associated with cancer metastasis and poor prognosis, its upregulation in gastric cancer patients is positively associated with poor prognosis and shorter survival." (PMID 34588926, 2021). "However, the role of cFOS and vinculin in cancer differs in different types of malignancies." (PMID 34588926, 2021). "Interestingly, force induced vinculin recruitment at the E-cadherin/β-catenin/α-catenin complex was shown to stabilize cell junctions in junction-poor cancer cells, a finding with intriguing implications for cancer metastasis." (PMID 32503141, 2020). "However, diverse reports can be found concerning the role of vinculin in cancer." (PMID 31877948, 2019). "Staining for vinculin and paxillin aligned with the peripheral degradation areas, suggesting that rheumatoid synovial fibroblasts may use both invadopodia and focal adhesions to degrade matrix, similarly to cancer cells." (PMID 25280866, 2014). "In the present study, VEGFA, RRM2, H2AFX, CHEK1, CEP55, CDCA8 and AURKA were significantly upregulated; however, VCL, TPM2 and TPM1 were significantly downregulated in cancer samples of BC." (PMID 34112125, 2021).
cancer (continued). "Taken together, PIPKIγ positively regulates focal adhesion dynamics and cancer invasion, most probably through PIP2-mediated vinculin activation." (PMID 21931851, 2011). "HSP90 was used as a control because GAPDH, cyclophilin A, and vinculin (data not shown) were increased under hypoxia in cancer cells." (PMID 34824343, 2021). "Recent studies have found that the absence of VCL expression in squamous epithelial tumors was related to the metastatic potential of tumors, and the overexpression of VCL in cancer cells can inhibit tumorigenic and metaplastic ability." (PMID 34923985, 2021). "Vinculin, a focal adhesion protein, was immunostained in nonsense siRNA-treated and VEGF siRNA-treated RFP-HeLa cells to examine the effects of VEGF depletion on the adhesive property of cancer cells." (PMID 25551022, 2014). "To ensure that the exogenous expression of the different proteins (e.g., FAK, ILK, etc.)did not contribute to FA stability, we expressed them in U2-OS human carcinoma cells without coexpressing active forms of vinculin and under tension-releasing drugs." (PMID 23375895, 2013). "Lamin-A, C profiles appear strikingly similar to those for the mechanosensitive factors Vinculin, Yap1, and Piezo1, whereas datasets for lamin-B1 align with and predict regulation by the cell cycle transcription factor, FOXM1, and further predict poor survival across multiple cancers." (PMID 35719698, 2022). "Recent studies have shown that the expression of VCL protein is decreased in squamous carcinoma, nonsmall lung cancer, breast cancer and other malignant tumors and is related to the enhanced invasion, metastasis and apoptosis of cancers." (PMID 34923985, 2021). "To test whether the stabilization of FAs by active vinculin is observed in different cell lines, we repeated our coexpression experiments with essentially the same results in NIH 3T3 mouse fibroblasts and U2-OS human carcinoma cells (data not shown)." (PMID 23375895, 2013).
tumor (87 papers, 2007 to 2025). "Tumor cells induce rapid endothelial cell dissociation, leading to the loss of VE-cadherin expression and changes in vinculin distribution and organization." (PMID 39035739, 2024). "The expression of vinculin can inhibit tumor invasion, whereas loss of vinculin promotes cell motility and migration." (PMID 30301189, 2018). "We found that loss of vinculin in MCF-7 cells promoted the instantaneous speed of tumour cells in the 3D matrix." (PMID 28266545, 2017). "A positive association was found between vinculin and ERα in both primary tumour (P<0.001, R2=0.528) and lymphatic metastasis (P<0.001, R2=0.366)." (PMID 28266545, 2017). "Expression of the MRTF-SRF transcription pathway-linked target genes, such as caldesmon, tropomyosin, vinculin, and zyxin, are reduced in certain tumor cells, and their forced re-expression reverses many malignant phenotypes of tumor cells." (PMID 27708220, 2016). "The phenotypic changes of reduced cell adhesion and an increase in cell motility associated with the loss of vinculin is thought to drive the formation of tumour metastases." (PMID 20655620, 2011). "However, in tumor tissue, all these associations were lost, except for a preserved inverse correlation between vinculin and transferrin (ρ = −0.355, p = 0.040)." (PMID 40507970, 2025). "Among the cytoskeletal-associated proteins that identified in conditioned medium of SCLC cell lines and that were elevated in both early stage and pre-clinical case plasmas were PFN1 and VCL, which have similarly been linked to promoting tumor progression and invasiveness." (PMID 34439128, 2021). "Vinculin, a coimmunoprecipitate—an intracellular F-actin-binding protein and a mechanotransducer in cell-cell and cell-matrix adhesions —has been implicated in tumor progression." (PMID 34010296, 2021). "Seven genes with tumor-specific splice variants were identified (Alpha-actinin 1, Caldesmon, Collagen, type VI alpha 3, Leucine-rich repeat interacting protein 2, Phosphatidylinositol-4 kinase catalytic beta polypeptide, Tropomyosin 1 and Vinculin)." (PMID 19516963, 2008). "In our model, the vinculin cytoplasmic increase and the corresponding reduction in the membrane content is suggestive of a loss of relationship with the surrounding environment, driving towards a form of independence which supports the evolution of the cell towards tumor characteristics." (PMID 39451527, 2024). "The binding of vinculin to F-actin suggested spatial differences in focal adhesion assembly and enlargement within the tumor." (PMID 40569470, 2025). "A significant decrease in vinculin expression was observed in tumor tissue compared with healthy mucosa (mean ± SD: 0.75 ± 0.51 vs. 1.46 ± 0.89, p < 0.001), as well as in vimentin (0.78 ± 0.80 vs. 4.08 ± 4.88, p < 0.001)." (PMID 40507970, 2025). "EMT-related proteins [mediator of ErbB2-driven cell motility 1 (MEMO1), E-cadherin, fibronectin, vimentin, and vinculin] were quantified by Western blotting in tumor and adjacent normal mucosa." (PMID 40507970, 2025). "Remarkably, the overexpression of VCL further intensified the tumor-suppressive effects elicited by CM." (PMID 38389836, 2024). "We also explored the underlying mechanisms of the tumor-suppressive effects of LIV-treated MSC CM, with a specific focus on vinculin (VCL)." (PMID 38389836, 2024). "The underlying reasons behind LIV's attenuation of force acting on VCL and the phenomenon of VCL overexpression in MSCs enhancing their LIV-driven anti-tumor potency remain elusive." (PMID 38389836, 2024). "To elucidate the mechanism underlying the VCL-driven augmentation of tumor-suppressive capabilities, we explored the impact of v-LIV on the expression levels of VCL within MSCs." (PMID 38389836, 2024).
tumor (continued). "Since cell-ECM interactions are largely regulated by focal adhesions, we determined if focal adhesions were different between leader and follower cells; thus we stained tumor organoids for vinculin, a known focal adhesion protein regulating migration." (PMID 38165954, 2024). "Compared to CM derived from control MSCs, our observations underscored that CM sourced from VCL-overexpressing MSCs exhibited notably augmented anti-tumor capabilities." (PMID 38389836, 2024). "It was unexpected that the proteins such as Hsp90ab1, Eno1, Eef2, and vinculin were enriched in the secretome since they are considered tumor promoters intracellularly 35-38." (PMID 35547745, 2022). "The results of increased vinculin levels with limited cell protrusions conform to the increased cell stiffness post-treatment with anti-tumor agents, indicating confined cell motility." (PMID 36052248, 2022). "These newly identified tumor suppressors, such as extracellular Eno1, Hsp90ab1, Eef2, and vinculin, downregulated Kdm3a, a histone demethylase, as well as the downstream oncogenic genes 21-24." (PMID 35547745, 2022). "Whole-genome proteomics predicted enolase 1 (Eno1), Hsp90ab1, Eef2, and vinculin as extracellular tumor suppressors." (PMID 35547745, 2022). "Vinculin is a major player in cell-matrix adhesion and intercellular adhesion, regulates the migration and invasion of tumor cells." (PMID 36457747, 2022). "As a mediator of force transfer between the extracellular matrix and cytoskeleton, vinculin promotes tumor cell invasiveness." (PMID 35454982, 2022). "A FRET vinculin biosensor assay demonstrated that the molecular force in tumor cells was weakened by osteocyte-derived CM." (PMID 34230453, 2021). "GEPIA database analysis indicated that those hub genes were significantly upregulated in the tumour tissues; however, VCL, TPM2, and TPM1 were significantly downregulated." (PMID 34112125, 2021). "In the past, vinculin was considered to be a tumor suppressor which inhibited tumor metastasis by supporting the growth of cells that rely on anchor connections and reducing cell viability." (PMID 33535187, 2021). "Animal studies have shown that adding miR-663b-containing exosomes to tumor tissues can reduce the expression of VCL protein and weaken angiogenesis, thereby inhibiting the growth of transplanted tumors in mice." (PMID 34923985, 2021). "To validate the SWATH-MS data using an orthogonal approach, we performed immunohistochemical (IHC) analysis of tumour cell expression levels of two proteins, vinculin (VCL) and decorin (DCN), in our cohort." (PMID 33895336, 2021). "The binding of vinculin to F-actin suggests spatial differences in focal adhesion assembly and enlargement within the tumor." (PMID 32793884, 2020). "This agrees with previous studies that show how, in tumor cells, vinculin is required for FA formation and regulates the clustering of integrin at cell membrane." (PMID 31945053, 2020). "Co-localization of vinculin with activated Akt was shown not only to promote tumor cell invasion but also contribute to extracellular matrix stiffness, which, in turn, promoted tumor progression in mammary epithelium." (PMID 31269666, 2019). "While the vinculin sensor is sensitive to tensile forces, tumor migration is an orchestrated process in which many motor and structural proteins are involved at focal adhesions and in the cytoplasm and nucleus." (PMID 30948840, 2019). "In conclusion, this study demonstrates that a vinculin tension sensor can be used to measure cell tensile forces to evaluate the behavior of tumor cells in tumor-osteocyte interactions." (PMID 30948840, 2019). "To characterize the vinculin tension sensor, we evaluated FRET efficiency in TMD tumor cells with reduced vinculin expression." (PMID 30948840, 2019). "As part of the molecular machinery regulating cellular motility, vinculin is reported to act as an inhibitor of tumor migration." (PMID 30948840, 2019).